STAT3 (signal transducer and activator of transcription 3)
Diseases named in the same sentence as STAT3 in open-access papers (continued):
Sharing a sentence is not in itself a finding about the gene and the disease.
cancer (continued). "Therefore, EPBS can potentially function as an anti-cancer agent by inducing apoptosis and autophagy when targeting the SHP-1/STAT3 pathway." (PMID 37762016, 2023). "NF-κB and STAT3 are major factors regulating CSC angiogenesis and invasiveness during cancer progression, and their activation and interaction play an important role in controlling communication between cancer cells and inflammatory cells." (PMID 37853413, 2023). "Moreover, STAT3 regulates both survival- and death-inducing autophagy in HCC and promotes cancer metastasis by inducing the epithelial-mesenchymal transition (EMT)." (PMID 37085753, 2023). "Some studies showed that curcumin could inhibit the proliferation and progression of several cancers by decreasing the expression of HIF-1α, STAT3, or VEGF signaling molecules, as well as inducing cell apoptosis." (PMID 37333486, 2023). "Mechanistically, UA inhibited inflammatory responses, decreased the concentration of cytokines in serum, and alleviated symptoms of cancer cachexia via activating SIRT1, thence downregulating the ubiquitin E3 ligase expression levels and the phosphorylation of NF-κB and STAT3." (PMID 37190306, 2023). "STAT3-overactive cancers can activate drug resistance genes like antiapoptotic BCL2, but inducing STAT3-dependent alkaliptosis may be a rational strategy to overcome this resistance." (PMID 37601110, 2023). "In addition, the distribution of STAT1, STAT2, STAT3, STAT4, STAT5A, STAT5B, and STAT6 expression in CD8+ T cells in pan-cancer were displayed, which presented that STAT1 and STAT2 had prominent up-regulation in CD8+ T cell with ISG IFIT1." (PMID 36968603, 2023). "Additionally, ROS promote the overactivation of cancer survival pathways, such as STAT-3, signal transducer and activator of transcription 3/VEGF, vascular endothelial growth factor, STAT-3/VEGF, signaling, that promotes angiogenesis." (PMID 36830028, 2023). "Moreover, inhibitors against STAT3, Pol I, and Pol III transcription would be combined and used in anti-cancer research in the future." (PMID 36656267, 2023). "Moreover, the activation of STAT3-regulated anti-apoptotic (Bcl-xL), cell proliferation (c-Myc), and angiogenic (VEGF) proteins, as well as the constitutively activated STAT3 protein, were all downregulated in response to AL in human SW620 cancer cells." (PMID 37242800, 2023). "While STAT3 inhibits antigen presentation and promotes the tolerogenic effects of myeloid cells, it is also required for the expansion of cytotoxic CD8 T cells in cancer patients and for the development and maintenance of memory T cells." (PMID 38259453, 2023). "In the CRC-HSCs interplay, CRC promoted HSCs-to-CAFs differentiation by releasing vascular endothelial growth factor (VEGF); and HSCs released interleukin 6 (IL6) that activated signal transducer and activator of transcription 3 (STAT3) in the CRC and hence increased the cancer metastatic potential." (PMID 37062842, 2023). "Furthermore, the repressed expressions of TGFb, STAT3 and elevated expressions of TNFa, IFNg, CXCR4 together promoted the anti-cancer efficacy." (PMID 37143538, 2023). "Our observations indicated that EPZ could effectively suppress both STAT3 phosphorylation and H3R2 methylation, subsequently countering the epithelial-mesenchymal transition in cancer cells." (PMID 37813837, 2023). "There is relatively little research on the anticancer activity of ATL III, which mainly inhibits cancer cell proliferation and promotes apoptosis primarily through the JAK3/STAT3 and miR-195-5p/FGFR1 signaling pathways to treat colon, gastric, lung, and liver cancers." (PMID 37241729, 2023). "Furthermore, the repressed expressions of growth factor TGFb, transcription factor STAT3 and elevated expressions of TNFa, IFNg, CXCR4 together promoted the anti-cancer efficacy." (PMID 37143538, 2023).
cancer (continued). "Although our study did not evaluate this finding, we might also hypothesize that, as LMP1 function depends on the NF-κB and STAT3 pathways, PDT might modulate LMP1 function via the STAT3 pathways in persistent cancer cells." (PMID 37239013, 2023). "As promising classical targets for the treatment of human cancers, several small molecule inhibitors targeting STAT3 and STAT5 have entered clinical trials, but none of them have been in clinical use." (PMID 37261210, 2023). "Surprisingly, an obvious decrease in JAK1 and STAT3 expressions was also observed in METTL3 knockdown cancer cells, but not in control groups." (PMID 38001065, 2023). "The inhibition of STAT3 activation may further inhibit AKT activation, suggesting the multifactorial nature of the efficacy of scopolamine D in inhibiting cancer cell lines." (PMID 38202691, 2023). "Despite the finding that the suppression of WNT/β‐catenin signaling on account of ectopic PRDM5 expression was determined in limited cancer cell lines, we first explored and identified the inhibition of JAK2/STAT3 pathway in LUAD cell lines with PRDM5 overexpression." (PMID 36127737, 2023). "Through the PI3K-Akt, HIF-1, and ErbB signaling pathways, curcuma regulates key targets that are involved in angiogenesis, cancer cell proliferation, metastasis, invasion, and chemotherapy resistance, including AKT1, TNF, STAT3, EGFR and HSP90AA1, in the treatment of OS." (PMID 37311820, 2023). "The abnormal expression of STAT3 is common in HCC, and this promotes cancer progression." (PMID 37762016, 2023). "Accumulating evidence suggests that ROCK1/2 upregulation contributes to the malignancy of breast, pancreatic, colorectal, and liver cancer through various signaling factors, including STAT3 and myosin light chain phosphatase 1 (MYPT1), thereby promoting cancer invasion and metastasis." (PMID 36982538, 2023). "Because HDAC3 has been reported to regulate the phosphorylation of STAT3 Y705 in other cancer types, we speculated that HDAC3 might influence the phosphorylation of STAT3 Y705 via activation of CDK1." (PMID 37743465, 2023). "Compared to the stringent control of PAR1 activation in normal tissues, PAR1 is constitutively overexpressed by cancer cells through activation of many downstream signaling cascades including the MMP1, signal transducer and activator of transcription 3 (STAT3), AKT, and VEGF pathways." (PMID 37667257, 2023). "It should be noted that ODZ is a STAT3 inhibitor and its inhibitory activity on both STAT3 and NLRP3 inflammasome might be beneficial to cancer treatment." (PMID 37047051, 2023). "Similarly, PARylation of transcription factor STAT3 by PARP1 has been reported to inhibit STAT3 transcriptional activity, and decrease the expression of PD-L1 in cancer cells." (PMID 37582914, 2023). "Therefore, it is apparent that YAP/STAT3/VEGF/VEGFR2, and other pathways are closely function in the regulating of the occurrence and development of cancer, while there are few studies on this pathway in BC." (PMID 37329188, 2023). "IL-37 shows a negative effect on cancer cell proliferation and invasion through the STAT3 signaling pathway." (PMID 36237303, 2022). "In addition, a cinnamaldehyde derivative (CB-PIC) was found to suppress P-glycoprotein expression by inhibiting JAK/STAT3 and PI3K/Akt signaling to overcome drug resistance in chemo-resistant cancer cells, thereby becoming an effective chemosensitizer." (PMID 36158694, 2022). "The Janus kinases (JAKs), which are non-receptor cytoplasmic tyrosine kinases, belong to the main promoters of STAT activation, whereas especially STAT3 and STAT5 of the total number of seven STAT-protein family members have been observed to be of greatest relevance in cancer development." (PMID 36185259, 2022).
cancer (continued). "Thus, SBT-100 is a “First-in-Class” anticancer agent for targeting STAT3 and KRAS simultaneously in cancers and provides proof of concept for this novel approach to treating cancer and other diseases by focusing on aberrant intracellular targets." (PMID 35886918, 2022). "Among these biomarkers, STAT3 and MYC can influence cancer cell survival and promote proliferation." (PMID 35743172, 2022). "Targeting cancer stemness is currently the basis of ongoing clinical trials on Phase III with paclitaxel/nab paclitaxel and gemcitabine with the addition of napabucasin, a small molecule that inhibits STAT3-mediated gene transcription." (PMID 36505808, 2022). "Network exploration suggested that VEGFA, STAT3, and PI3KCA may be candidate agents for the antibladder cancer effect of gypenosides." (PMID 35402614, 2022). "Thus, activated STAT3 can promote EMT and maintain the stemness of cancer stem cells, thereby affecting the prognosis of patients with cancer." (PMID 35356799, 2022). "STAT3 has gained significant attraction as an actionable anti-cancer therapeutic; however, there are currently no FDA-approved STAT3-targeted therapies for the treatment of cancer." (PMID 35371975, 2022). "Therefore, a combination of LY5 (STAT3 inhibitor) and trametinib (MEK inhibitor) was administered to assess anticancer efficacy in resistant cancer." (PMID 36145523, 2022). "We found that EPP suppressed the activity of STAT3 and AKT, pivotal regulators of cancer cell survival and growth, suggesting that these molecules could mediate the anticancer effects of EPP." (PMID 35408753, 2022). "Increased levels of STAT3 and JAK phosphorylation in CAAs may led to the production of IL-6, which promotes cancer cell survival, immune suppression, and drug resistance." (PMID 36226048, 2022). "IL-17 has been found to promote migration, extracellular matrix degradation, and invasion of cancer cells, including GBM cells, through the activation of PI3K–AKT and STAT3 signaling, as well as through the elevation of expression of the matrix metalloproteinases MMP-2 and MMP-9." (PMID 35884700, 2022). "In brief, DUSP1, ZFP36, SLC2A3, HMGB1, STAT3, MT3, and ALOX5 were all FRGs that might be involved in cancer development and immune regulation." (PMID 36131791, 2022). "DRD2 antagonists could also induce M1-polarization of macrophages and decrease PD-L1 expression in cancer cells via inhibition of ERK and STAT3 signaling pathways." (PMID 36072788, 2022). "Despite being considered as a therapeutic target for cancers, attempts to target STAT3 as we have discussed have not met with much success, due to poor target specificity and ineffectiveness in blocking the transcriptional activity of the monomeric form." (PMID 35844493, 2022). "Our results suggest that the novel α5-nAChR/STAT3-Jab1-PD-L1 axis is involved in LUAD immune escape, which could lead to potential therapeutic strategies for cancer immunotherapy." (PMID 35971127, 2022). "Numerous reports showed that non-receptor tyrosine kinase SRC is involved in oncogenic STAT3 activation across various human cancers." (PMID 36324587, 2022). "While our concept targets activated STAT6, PROTAC, as designed for STAT3 in cancer, for instance, does not differentiate between active vs. inactive transcription factors." (PMID 36348405, 2022). "Fusing the transcriptional inhibitory domain KRAB with STAT3 successfully blocked the transcription activity of STAT3 in cancer cells without affecting its function in the mitochondria and lysosomes." (PMID 35810312, 2022). "Furthermore, the deregulation of miR-221-3p expression is involved in the regulation of the suppressor of cytokine signaling 3/signal transducer and activator of transcription 3 (SOCS3/STAT3) pathway, which is particularly relevant in cancer resistance." (PMID 35681658, 2022).
cancer (continued). "To investigate this hypothesis, we generated cancer lines conditionally expressing oncogenic forms of MET effectors KRAS, PI3K, and STAT3 (p20-KRASG12D, p20-PIK3CAE545A, and p20-STAT3A662C_N664C)." (PMID 35326531, 2022). "Cell survival and proliferation, proinflammatory cytokine expression and TGR5/STAT3/KLF5 axis activity were measured in normal human gastric cells, cancer cells, and organoid lines derived from C57BL/6, FVB/N and insulin-gastrin (INS-GAS) mice treated with DCA." (PMID 36067404, 2022). "Interestingly, andrographolide is known to inhibit the actions of STAT3, JAK1, and JAK2 phosphorylation in human cancer cells." (PMID 35682652, 2022). "It is shown that anti-cancer effects of (−)-Epigallocatechin gallate (EGCG), the most abundant catechin in tea, are performed through inhibition of phosphorylation and expression of both JAK3 and STAT3 proteins." (PMID 36581900, 2022). "Furthermore, to check the activity of azilsartan in both cancer cell lines at the molecular level, NF-kB/IL-6/JAK2/STAT3 signaling pathway was investigated." (PMID 36431925, 2022). "A short treatment with two specific STAT3 inhibitors significantly reduced HIF-1α in BM macrophages after a 2 hr incubation with apoptotic cancer cells; however, HIF-1α stabilization was not completely abrogated." (PMID 36496973, 2022). "Cancer cells lacking phospho-serine (p-Ser) 727 STAT3, a modification known to be critical for mitochondrial translocation, were more sensitive to oxidative stress than intact cells." (PMID 35928250, 2022). "As a result, quercetin’s anti-inflammatory and anti-apoptotic properties play an important role in cancer prevention by modulating the TLR-2 (toll-like receptor-2) and JAK-2/STAT-3 pathways and significantly inhibiting STAT-3 tyrosine phosphorylation within the inflammatory cells." (PMID 36233051, 2022). "Given the fact that IL-6 was one of the most induced cytokines in the context of cancer immunotherapy (ICB and adoptive therapy), we wanted to evaluate whether the IL-6/STAT3 axis could in fact be upregulating SMG1." (PMID 36443756, 2022). "Inhibition of MAPK pathway, STAT3 activation and down-regulation of ER signaling pathway in the genome seems to be an important mechanism by which hesperidin induces apoptosis or autophagy in ECC-1 cancer cells." (PMID 36080397, 2022). "Therefore, fisetin induced apoptosis in TPC-1 cancer cells via the initiation of oxidative damage and the enhancement of the caspase expression through controlling JAK 1 as well as STAT3 signaling molecules." (PMID 36558146, 2022). "Curcumin has been shown to induce cancer cell autophagy by inhibiting the PKB/mammalian target of rapamycin (mTOR)/p70S6 pathway and MAPK1/2 pathway and inhibits signalling protein STAT3 by suppressing the IL6-mediated phosphorylation of STAT3." (PMID 35663647, 2022). "Marginean at al. assessed the nuclear expression of STAT3 phosphorylated at Tyr705 and Ser727 in the prostate stromal compartment of the cancer and non-cancer areas in hormone-naive patients after a radical prostatectomy due to localized PCa." (PMID 36230984, 2022). "We chose to target STAT3 because there is no direct STAT3 inhibitor available in clinical practice, although this TF is one of the most attractive target for cancer therapy." (PMID 35847174, 2022).
cancer (continued). "In the hypercholesterolemic urinary bladder cancer (UBC) mouse model, ezetimibe significantly suppress HFHC-induced serum lipid (TC, LDL-C, and ox-LDL), and decrease the percentage of cancer cells (CK5+, CK14+, and p-STAT3+) and cancer stemness markers (ALDH1A1, CD44, KLF4, and Nanog)." (PMID 35924044, 2022). "Therefore, we confirmed that STAT3 can regulate ICAM-1 expression by forming a positive feedback loop in CRC, identical to other cancer types." (PMID 35487888, 2022). "Thus, we are the first to propose a new UHMK1/STAT3 positive feedback loop to augment JAK/STAT3 signaling and lead to cancer development and progression." (PMID 35501324, 2022). "Furthermore, STAT3 phosphorylation leads to the activation of atrogin‐1, MuRF‐1, and MSTN in cancer patients with cachexia." (PMID 36127129, 2022). "ACN appears to be a novel STAT3 inhibitor and may be a promising therapeutic compound for application in the treatment of HCC and other cancers." (PMID 36080130, 2022). "STAT3 is widely recognized as a master regulator and driver of transforming events leading to GBM, and has been studied as a prognostic marker and therapeutic target in GBM and other cancers." (PMID 35387234, 2022). "In contrast, expression of Stat1 was increased in cancer cells of Tyk2ΔIEC tumors while expression of Stat3 and activation of Stat1 and Stat3 were not altered." (PMID 36185806, 2022). "Indeed, STAT3 acts as a transcriptional activator of the UPS proteolytic pathway and has been demonstrated to trigger autophagy during cancer." (PMID 35847939, 2022). "In addition, several signaling pathways, including MAPK/JNK and JAK2/STAT3, for SK1 in cancer have been described." (PMID 36500220, 2022). "The purpose of inhibiting STAT3 activation, P-GP and FUT4 expressions in A549/T cells was to overcome the resistivity, as these proteins are considered to be the major contributors in developing preventive strategies by cancer cells against paclitaxel." (PMID 35281907, 2022). "From cancer studies, it was established that eEF1A proteins can promote cell growth and proliferation by serving as an upstream activator of PI3K/AKT/mTOR and/or PI3K/AKT/STAT3 pathways." (PMID 36123349, 2022). "By blocking acetylated STAT3 dimerization and DNMT1 interaction SHF may serve as an attractive therapeutic target for patients with a range of cancers, not only GBM." (PMID 35843865, 2022). "Moreover, CD44 and Stat3 acted as the top DEPs, and the expression and activity of which are correlated with EMT in different cancers." (PMID 36678534, 2022). "Since HER-2 is not expressed in TNBC diagnosis, the production of nanobodies for the diagnosis and treatment of cancer cells should be performed against other antigens expressed in TNBC such as TNF-α, EGFR, CD3, CTLA-4, STAT3, AKT2, GTP-binding protein Rho, CapG, fibronectin, and CA-IX." (PMID 35933373, 2022). "Accordingly, we assumed that after p-STAT3 signaling was activated, the cytoplasmic LMO2-LDB1 complex was formed as a result of the increased level of LMO2 through positive feedback to maintain the cancer stem-like properties of the cancer cells." (PMID 36359204, 2022).